CACNA2D2 (calcium voltage-gated channel auxiliary subunit alpha2delta 2)
Diseases named in the same sentence as CACNA2D2 in open-access papers (continued):
Sharing a sentence is not in itself a finding about the gene and the disease.
tumor (15 papers, 2007 to 2025). "By combining these gene sets, we identified the leading genes that were associated with the tumor laterality: CACNA1C, CACNA2D2, CACNB2, KCNJ11, SCN3A, and SCN3B, signature that we called: 6-ICH signature." (PMID 37446299, 2023). "A few differentially expressed genes between the PitNET subtypes also correlate with tumor size (CACNA2D2, CGA, KRT8, RALGAPA2) suggesting a potential role in tumor growth." (PMID 34758873, 2021). "To further study the oncogenic link between the up-regulation of CDC42 and subsequent silencing of CACNA2D2 in vivo, we further characterized the tumor xenografts generated by CDC42 for CDC42 and CACNA2D2 expression." (PMID 28460460, 2017). "Many genes in these chromosome lesions, such as EGFR (amp 7p11.2), MET (amp 7q31.2), KRAS (amp 12p12.1), and CACNA2D2 (del 3p21.31), are known to be related to tumor invasion and metastasis." (PMID 28922552, 2017). "CACNA2D2 gene, a subunit of the voltage-dependent calcium channel complex, is located in the 3p21.3 chromosomal region, a known tumor suppressor gene cluster, that also includes LARS2." (PMID 28460460, 2017). "Three genes (CACNA1D, CACNA2D1, and CACNA2D2) coding for the α subunit of voltage-dependent Ca2+ channels were down-regulated in tumor tissues." (PMID 24466154, 2014). "Many tumor suppressorcandidate genes such as CACNA2D2, DLC1, FUS1, H37, HYAL1, RASSF1A, SEMA3B, andSEMA3F and tumor susceptibility genes such as hMLH1 have been isolated from theregion." (PMID 18288251, 2007). "Moreover, both bulk‐ and sc‐derived CACNA2D2 signatures precisely distinguished DSRCT cell clusters from non‐tumor cells in single‐cell RNA‐sequencing (scRNA‐seq) data from four DSRCT patients (n = 11 samples)." (PMID 40088092, 2025). "Two genes, Cacna2d2 and Dbc1 are candidate tumour suppressors in other cancers." (PMID 28577549, 2017). "The statistical correlation between CDC42 and CACNA2D2 in the tumor samples was also investigated." (PMID 28460460, 2017). "and CACNA2D2 with genomic lesions might play key roles in driving tumor metastasis." (PMID 28922552, 2017). "Given the genetically independent nature of MM tumours and the low likelihood of the same gene being mutated at different positions in more than one sample, the presence of different mutations in Nkd1 in two BALB/c samples and Cacna2d2 in samples from two different strains is informative." (PMID 28577549, 2017). "Future studies should investigate the precise role of CACNA2D2 in DSRCT biology, with a focus on its potential contributions in tumor cell fitness, differentiation, and tumorigenic potential." (PMID 40088092, 2025). "In this validation cohort, survival analysis was intentionally restricted to the subgroup of patients with Dukes ́ C and D tumor, where a significant interaction between the expression of CDC42 and CACNA2D2 was found." (PMID 28460460, 2017). "We found that CACNA2D2 was down-regulated in five out of 7 CRC cell lines (71%), supporting a potential role as TSG in this tumor type." (PMID 28460460, 2017). "The candidate region on 3p21.3 harbors various tumor suppressor genes (HYAL2, FUS1, RASSF1, BLU, NPR2L, CYB561D2, PL6 and CACNA2D2)." (PMID 20678252, 2010). "Interestingly, when compared to CDC42 shRNA cells before injection, CACNA2D2 expression was down-regulated in the CDC42 shRNA derived tumors to levels comparable to the parental CDC42-wt1 cell lines before injection and their corresponding tumor samples." (PMID 28460460, 2017).
cancer (11 papers, 2010 to 2025). A tumor composed of atypical neoplastic, often pleomorphic cells that invade other tissues. "CACNA2D2 is a tumor suppressor gene in several types of cancer, however its role in CRC or correlation with CDC42 has not been described yet." (PMID 28460460, 2017). "Interestingly, CACNA2D2-induced increase of cytosolic-free Ca2+ content was observed in cancer cells." (PMID 33308295, 2020). "The upregulation of CACNA2D2 by TSPX may reinforce the inhibition of cancer development." (PMID 39858622, 2025). "Altogether, we show that CDC42 has an active oncogenic role in CRC via the transcriptional regulation of multiple cancer-related pathways and that CDC42-mediated silencing of CACNA2D2 is clinically relevant." (PMID 28460460, 2017).
infection (2 papers, 2019 to 2021). The state of being infected such as from the introduction of a foreign agent such as serum, vaccine, antigenic substance or organism. "Similarly, LUJV infection was inhibited following the knockdown by siRNA of either CACNA1S or CACNA2D2, indicating that VGCC is critical for LUJV entry." (PMID 34925303, 2021).
neurological diseases (2 papers, 2020 to 2026). "Although there are no reported studies on the relationship between CACNA2D2 and SCZ, CACNA2D2 may cause other psychiatric disorders and severe neurological diseases." (PMID 32071821, 2020).
CACNA2D2 also shares sentences with these, for which no sentence is quoted: developmental delay (4 papers); Alzheimer disease (2); autism spectrum disorder (2); cerebellar ataxia (2); Cognitive impairment (2); Parkinson disease (2); triple-negative breast carcinoma (2); amyotrophic lateral sclerosis (1); Anxiety (1); arrhythmogenic right ventricular cardiomyopathy (1); Autoimmunity (1); brain injury (1); cardiac arrhythmias (1); cardiomyopathy (1); CNS lymphoma (1); colon cancer (1); convulsion (1); COVID-19 (1); developmental and epileptic encephalopathy (1); Dravet syndrome (1); Dyskinesia (1); endometrial cancer (1); gastric cancer (1); head and neck squamous cell carcinoma (1); Hyperglycemia (1); hypertrophic cardiomyopathy (1); infantile epileptic encephalopathy (1); Intellectual disability (1); musculoskeletal system diseases (1); nasopharyngeal carcinoma (1).
A further 12 diseases each share a sentence with CACNA2D2 in 1 paper.